GZMA (granzyme A)
Diseases named in the same sentence as GZMA in open-access papers (continued):
Sharing a sentence is not in itself a finding about the gene and the disease.
Salmonella Infections (2 papers, 2024 to 2025). Infections with bacteria of the genus SALMONELLA. "Upon oral Salmonella infection, GzmA KO mice suffered more weight loss and marginally higher bacterial burdens than WT mice." (PMID 39137883, 2024). "GzmA-mediated cell death is very effective in controlling epithelial Salmonella infection both in vitro and in vivo." (PMID 39137883, 2024). "In summary, these data indicate that GzmA/B specifically protect small intestinal epithelial cells from Salmonella infection, showing that the route and site of infection are important factors in the immune response to pathogenesis." (PMID 39137883, 2024). "Interestingly, differential gene expression analysis between the two conditions (F1-SSP versus ΔTreg SSP), irrespective of clustering, highlighted granzyme A and B as highly expressed genes in the absence of Tregs during Salmonella infection compared with F1-SSP hosts." (PMID 40924026, 2025).
systemic sclerosis (2 papers, 2016 to 2025). A chronic disorder, possibly autoimmune, marked by excessive production of collagen which results in hardening and thickening of body tissues. "Existing research indicates that the granzyme A gene is expressed in systemic sclerosis, suggesting that granzyme mediates ECs injury, but whether AECAs are induced by granzyme A expression has not been functionally confirmed." (PMID 40370444, 2025).
typhoid fever (2 papers, 2021 to 2024). A bacterial infectious disorder contracted by consumption of food or drink contaminated with Salmonella typhi. "Importantly, our work establishes a new paradigm in which a perforin-independent role of GzmA and GzmB mediates protection against enteric Salmonella infection, and provides a rational explanation for the high levels of extracellular GzmA seen in patients with typhoid fever." (PMID 39137883, 2024).
ulcerative colitis (2 papers, 2024 to 2025). An inflammatory bowel disease involving the mucosal surface of the large intestine and rectum. "The DRB1*01:03 allele—which is thought to be a risk allele for ulcerative colitis (UC) based on prior GWAS39—was associated with both UC and the expression of several inflammatory proteins such GZMA, GZMH, and IL10." (PMID 39085222, 2024).
Achalasia (1 paper, 2023). A disorder of esophageal motility characterized by the inability of the lower esophageal sphincter to relax during swallowing and by inadequate or lacking peristalsis in the lower half of the body of the esophagus. "However, several cytotoxic enzymes and inflammatory cytokines, including GZMA, GZMB, GZMK, GNLY, and TNF were downregulated in TRM in achalasia, consistent with a previous study of TRM in MS42." (PMID 37542039, 2023).
allergic asthma (1 paper, 2025). A asthma with a basis in a pathological type I hypersensitivity reaction. "This aligns with the observed downregulation of granzyme A signaling, suggesting that ITIH4 may attenuate cytotoxic immune responses in allergic asthma." (PMID 40410722, 2025).
alopecia areata (1 paper, 2026). Loss of scalp and body hair involving microscopically inflammatory patchy areas. "Compared with healthy controls, mRNA levels of EOMES, GZMA, IL2RB, and IL2RG were significantly upregulated in alopecia areata (AA) lesional scalp (all p<0.01), whereas androgenetic alopecia (AGA) scalp showed no significant increase relative to controls (all p>0.05)." (PMID 41602548, 2026).
B-cell NHL (1 paper, 2025). "Hence, an abundance of GZMA+GZMK+ cytotoxic CD4+ and CD8+ T cells was associated with poor survival of B-cell NHL patients." (PMID 41030456, 2025).
bovine tuberculosis (1 paper, 2012). "Thus, murine transcriptome analysis can be used to predict immunological responses in cattle allowing the prioritisation of CXCLl9, CXCL10, Granzyme A and IL-22 as potential additional readout systems for the ante-mortem diagnosis of bovine tuberculosis." (PMID 22359547, 2012).
Cachexia (1 paper, 2022). Severe weight loss, wasting of muscle, loss of appetite, and general debility related to a chronic disease. "Indeed, differential gene expression analysis of CD8+ T cells showed significantly higher expression of genes representing activated state in cachexia patients, including GZMH, GZMA, NKG7, and IFNG." (PMID 36376273, 2022).
cardiomyopathy (1 paper, 2015). A disease of the heart muscle or myocardium proper. "Interestingly, in CD patients with severe cardiomyopathy the presence of cells expressing granzyme A (another component of the lytic machinery of CTL CD8+ T-cells) in heart lesions is in accordance with concepts that involve cytolysis in pathogenesis of CCC." (PMID 25789471, 2015).
cervical cancer (1 paper, 2022). A primary or metastatic malignant neoplasm involving the cervix. "constructed a new prognosis predication model based on 8 risk-related PRGs (GPX4, GSDME, GZMA, GZMB, IL1B, NOD1, PRKACA, and TNF) in cervical cancer, which had good predictive ability (AUC = 0.794)." (PMID 35912258, 2022).
chronic apical periodontitis (1 paper, 2023). Chronic form of periapical periodontitis. "This study aimed to investigate the role and mechanism of the serine protease GZMA in osteoclasts during chronic apical periodontitis." (PMID 37626297, 2023).
coronary artery disease (1 paper, 2022). "High levels of circulating GZMA have been found in patients with coronary artery disease and were verified to correlate with the severity of the disease." (PMID 35498008, 2022).
diabetes mellitus (1 paper, 2012). A metabolic disorder characterized by abnormally high blood sugar levels due to diminished production of insulin or insulin resistance/desensitization. "Granzyme A is expressed in and surrounding the islets during the development of spontaneous diabetes mellitus in the non-obese diabetic mouse." (PMID 22384093, 2012).
diabetic nephropathy (1 paper, 2025). "The expression levels of IL7R, CD2, GZMA, CD3D and FCER1A significantly differed between diabetic nephropathy and controls." (PMID 41332907, 2025).
Disorders of the Basal Ganglia (1 paper, 2019). "Both groups of regulated proteins had canonical pathways involved in Granzyme A signaling and functional annotations involved in Disorders of the Basal Ganglia or Movement disorders." (PMID 30629705, 2019).
endometrial tumors (1 paper, 2021). "To understand the underlying mechanisms involved in the suppression of CD8+ T cell cytotoxic killing in endometrial tumors, we investigated whether there were changes in the expression of granzyme A (GZA), granzyme B (GZB), perforin (PRF), and PD-1 in CD103+ and CD103-CD8+ T cells." (PMID 33968059, 2021).
epilepsy (1 paper, 2025). A brain disorder characterized by episodes of abnormally increased neuronal discharge resulting in transient episodes of sensory or motor neurological dysfunction, or psychic dysfunction. "In our study, GZMA is most closely associated with CD8+ T cells, both in the blood of epilepsy patients and in the hippocampus of epilepsy models." (PMID 39753851, 2025). "We found that CDC25B, DNMT1, GZMA, MTX1, and SSH2 expression decreases epilepsy risk, whereas FGD3, RAF1, and SH3BP5L increase it." (PMID 39753851, 2025).
Flavivirus Infections (1 paper, 2013). Infections with viruses of the genus FLAVIVIRUS, family FLAVIVIRIDAE. "Cytolytc leukocytes such as CD8+ T cells induce cytopathology during some encephalitic flavivirus infections and these leukocytes kill virus-infected cells using two distinct mechanisms viz., Fas and granular exocytosis which involve perforin, granzyme A and B." (PMID 23940775, 2013).
glioblastoma (1 paper, 2022). The most malignant astrocytic tumor (WHO grade IV). "Conversely, higher expression levels of GSDMB, GZMA, and GZMB were detected in T cells, whereas NLR4 and CASP5 showed specifically high expression levels in TAMs, and CASP5, GZMA, GZMB, and NLRC4 were barely detected in glioblastoma cells." (PMID 35990696, 2022).
Herpesvirus infection (1 paper, 2023). "GZMA is a factor related to cytotoxicity following Herpesvirus infection and its levels are increased in effector memory T cells from AD patients." (PMID 37179358, 2023).
HIV-1 infection (1 paper, 2017). The type species of lentivirus and the etiologic agent of acquired immunodeficiency syndrome (AIDS). "Interestingly, HIV-1 infection triggered a significant increase in granzyme A, B and H expression in LP CD4+ T cells, which we confirmed at the protein level by flow cytometry." (PMID 28241075, 2017).
Insulin resistance (1 paper, 2011). Increased resistance towards insulin, that is, diminished effectiveness of insulin in reducing blood glucose levels. "Examples of other pro-inflammatory proteins affiliated with inflammation but not liver insulin resistance were cathepsin S or granzyme A." (PMID 21978410, 2011).
ischemic stroke (1 paper, 2014). A stroke disorder caused by obstruction of blood flow to the brain, due to thrombotic (local blood clot formation) or embolic (due to a blood clot or other material traveling from another site) event. "Notably, in our previous study of human peripheral blood leukocytes following ischemic stroke, we also observed sexually dimorphic cell death pathways with females showing Caspase 1, HMGB1, and NFkB Signaling pathways, while in males Granzyme A signaling and other cell death molecules were involved." (PMID 25036109, 2014).
kidney stone (1 paper, 2025). "Concurrently, six protein ratio pairs were found to inhibit kidney stone occurrence: GGT1/MME protein level ratio, ACE2/MME protein level ratio, ITIH3/VCAM1 protein level ratio, GZMA/TNFRSF8 protein level ratio, CRADD/HSPA1A protein level ratio and GZMA/TNFRSF4 protein level ratio." (PMID 40673688, 2025).
leishmaniasis (1 paper, 2021). Infectious disease that is transmitted through the bite of hematophagous female phlebotomine sand flies. "Interestingly, VL patients also exhibit higher expression of GZMA, GZMB, and PRF1 in the blood compared to healthy subjects, indicating a potential common cytolytic response in leishmaniasis." (PMID 33793565, 2021).
liver cancer (1 paper, 2021). An epithelial or non-epithelial malignant neoplasm that arises from the liver. "The differences in protein levels of C1QC, CD3D, GZMA, and PSMB9 in different liver cancer stages were determined using immunohistochemistry." (PMID 34124275, 2021).
lymphopenia (1 paper, 2017). Reduction in the number of lymphocytes. "(The initial drop in granzyme A levels in NHPs 3, 5, 6 and 7 on day 2 coincides with the transient lymphopenia often seen at this time)." (PMID 28207896, 2017).
medulloblastoma (1 paper, 2025). A malignant, invasive embryonal neoplasm arising from the cerebellum. "GZMA: GZMA is not detected in both tumor tissues and normal tissues (HPA054134), suggesting that it may have limited involvement in the medulloblastoma tumor microenvironment." (PMID 40104502, 2025).
myopia (1 paper, 2025). "Similarly, granzyme A in the retina was found to be activated in the lens-induced myopia (LIM) model, which may be involved in myopia progression by activating cellular caspase-independent apoptosis and modulating inflammation." (PMID 41191163, 2025).
onchocerciasis (1 paper, 2018). Onchocerciasis is a form of filariasis, caused by the parasitic worm Onchocerca volvulus, transmitted by the black fly. "For example, in onchocerciasis, Granzyme A/B expression was associated with Treg induction and subsequent immune suppression." (PMID 29668679, 2018).
parathyroid tumors (1 paper, 2024). "Additional research is needed to characterize the functional significance of hypermethylation in genes related to eukaryotic initiation factor 2 (EIF2), oxidative phosphorylation, and granzyme A pathways in the tumorigenesis of menin-deficient parathyroid tumors." (PMID 39336822, 2024). "The genes frequently hypermethylated in menin-deficient parathyroid tumor tissue are most highly associated with the eukaryotic initiation factor 2 (EIF2), Wnt/β-catenin, oxidative phosphorylation, and granzyme A pathways." (PMID 39336822, 2024).
pulmonary fibrosis (1 paper, 2024). Chronic progressive interstitial lung disorder characterized by the replacement of the lung tissue by connective tissue, leading to progressive dyspnea, respiratory failure, or right heart failure. "In contrast to aged versus young, aged versus middle-aged unstimulated upregulated genes displayed major changes in different pathways, including IL-17 A signaling, PTEN, Granzyme A, TGF-β and pulmonary fibrosis." (PMID 38515147, 2024).
rectal cancer (1 paper, 2022). A primary or metastatic malignant neoplasm that affects the rectum. "Gene expression levels of GZMA, GZMB, PRF1, IFNG and chemokine CXCL10 were compared between responsive versus non-responsive rectal cancer patients." (PMID 35534879, 2022).
renal cell carcinoma (1 paper, 2023). "In A clinical study of 22 patients with renal cell carcinoma before and 3 months after cryoablation and blood samples of some patients, it was found that CD8+T, CD4+T, granzyme A(GZMA), CD11c transcription levels were significantly increased, and CD8/FOXP3 was increased after cryoablation." (PMID 36761748, 2023).
renal fibrosis (1 paper, 2024). A final common manifestation of a wide variety of chronic kidney diseases characterized by glomerulosclerosis and tubulointerstitial fibrosis. "Targeting specific immune cells, like reducing CD33dim HLA DR + CD11b + AC MDSCs to lower renal fibrosis risk and inhibiting granzyme A (GZMA) in NK cells to reduce inflammation, shows promise." (PMID 39014501, 2024).
respiratory failure (1 paper, 2021). The significant impairment of gas exchange within the lungs resulting in hypoxia, hypercarbia, or both, to the extent that organ tissue perfusion is severely compromised. "Respiratory failure was signified by depression of EGF, GZMA, LAP, IL-4, and IL-7, and increased expression of MUC-16, ARG-1, and LAMP-3." (PMID 34177897, 2021).
septic peritonitis (1 paper, 2017). Septic peritonitis is an inflammatory condition of the peritoneum that occurs secondary to microbial contamination. "In the present study, we report the intracellular expression of gzmA and gzmB and their function in a mouse model that resembles the clinical condition commonly associated with septic peritonitis by E. coli." (PMID 28694562, 2017). "For this purpose, we used a murine model of E. coli intraperitoneal infection, resembling the clinical condition commonly associated with septic peritonitis by this bacterium, in wild-type and gzmA-deficient (gzmA−/−), gzmB−/−, and gzmAxB−/−mice." (PMID 28694562, 2017). "To get insight into the influence of gzmA and gzmB deficiency on the local inflammatory response elicited during septic peritonitis, we measured proinflammatory (TNF-α, IFN-γ, and IL-1β, IL-6) and anti-inflammatory (IL-10) cytokines as well as MCP-1 and KC levels in PLF." (PMID 28694562, 2017).
tauopathy (1 paper, 2024). Neurodegenerative disorders involving deposition of abnormal tau protein isoforms (tau proteins) in neurons and glial cells in the brain. "Development of a semi-targeted mass spectrometry approach identified peptides in tauopathy brain tissue corresponding to proteolysis by GzmA at R209-S210 and K240-S241 in tau." (PMID 39248243, 2024). "Using a semi-targeted mass spectrometry (MS) approach we show that peptides corresponding to proteolytic cleavage of tau by GzmA are present in the brain in tauopathies." (PMID 39248243, 2024). "Mass spectrometric analyses indicates that tau fragments with proteolytic cleavage sites corresponding to the action of GzmA are present in the tauopathy brain." (PMID 39248243, 2024). "GZMA transcripts have been detected in tauopathy brains and GzmA was localised by immunohistochemistry to CD8+ T cells in the hippocampus of an AD-affected brain." (PMID 39248243, 2024). "Genetic knockdown of GzmA in animal models of tauopathies could be used in future studies to confirm a role for the protease in the proteolytic cleavage of tau and the impact this has on the development of neurodegeneration." (PMID 39248243, 2024). "The phosphorylation, aggregation and seeding data indicate that GzmA-cleaved C-terminal tau fragments have an increased likelihood to aggregate, to propagate tau aggregation and transcellularly spread, and thus that proteolysis of tau by GzmA could facilitate pathogenesis in tauopathies." (PMID 39248243, 2024). "Collectively, these results raise the possibility that GzmA, released from infiltrating cytotoxic CD8+ T cells, proteolytically cleaves tau into fragments that may contribute to its pathological properties in tauopathies." (PMID 39248243, 2024).
thymoma (1 paper, 2025). A neoplasm arising from the epithelial cells of the thymus. "GZMA CNVs were notably associated with survival in multiple cancers, including KIRP, THCA, thymoma, KICH, UCEC, KIRC and SARC." (PMID 40002821, 2025).
type 1 diabetes (1 paper, 2025). "GZMA was previously reported in pediatric type 1 diabetes and it was also recognized as a proinflammatory mediator contributing to overreaction of the immune system with a reduced inflammatory response." (PMID 39847262, 2025).
uveitis (1 paper, 2023). An inflammatory process affecting a part of or the entire uvea. "In contrast, uveitis in the BD patient had few of these effector CD4+ T cells but was characterised by clonally expanded effector CD8+ T cells expressing CCL5, GZMA, GZMB and PRF1." (PMID 37720629, 2023).
vitiligo (1 paper, 2024). Generalized well circumscribed patches of leukoderma that are generally distributed over symmetric body locations and is due to autoimmune destruction of melanocytes. "Here, we document a sequence of immunologically significant events, including characteristic rises in infiltrating B and αβ T cells as well as evidence of active leukocyte recruitment and cell-mediated immune activities (CCL19, IFNG, GZMA) leading up to visual vitiligo onset." (PMID 38720888, 2024). "A microarray study examining pools of cDNA from growing feathers of Smyth chickens collected before and at disease onset found evidence of both humoral (Ig-J chain, CXCL13) and cell-mediated (CCL19, GZMA, IL21R) immune activities prior to vitiligo onset." (PMID 38720888, 2024). "Highly significant changes in the expression of T cell activation-related genes IFNG, FASLG, GZMA and IL21 and anti-inflammatory genes IL10 and TGFB1 were found in growing feathers of vitiligo-expressing Smyth chickens (P < 0.0001)." (PMID 38720888, 2024).
Yersinia infections (1 paper, 2024). "Yersinia infections in macrophages trigger caspase-8 cleavage of GSDMD, which in turn initiates pyroptosis, and granzyme A, a lymphocyte-derived enzyme, cleaves GSDMB, which in turn triggers pyroptosis in a number of cancer cell types." (PMID 39655049, 2024).